INS (insulin)
Diseases named in the same sentence as INS in open-access papers (continued):
Sharing a sentence is not in itself a finding about the gene and the disease.
diabetes (continued). "In fact, diabetes is a chronic and metabolic disease that occurs when the pancreas does not produce enough insulin or the body does not properly use the insulin it produces." (PMID 36297570, 2022). "Multivariate logistic regression showed that PA was also negatively correlated with insulin levels in participants without diabetes." (PMID 35185617, 2022). "In diabetes, the normal harmony between GLUT4 and insulin activity is disrupted." (PMID 36438767, 2022). "Recent advancements in hPSCs technology have enabled direct differentiation to human islet-like clusters, which can sense glucose and secrete insulin, and those islet clusters can ameliorate diabetes when transplanted into rodents or non-human primates (NHPs)." (PMID 35557947, 2022). "There were also positive correlations with serum insulin in diabetes and albumin (weak correlation each), but HDL-c was not correlated with biochemical parameters." (PMID 35462799, 2022). "As expected, high fat feeding increased body mass and glucose and insulin levels compared to Std, but glucose levels were not high enough to indicate diabetes (fasting glucose approximately 230 mg/dl in mice)." (PMID 36082224, 2022). "As metformin acts primarily to inhibit gluconeogenesis, its ability to lower blood glucose and insulin concentrations is likely minimal under postprandial conditions in individuals without diabetes." (PMID 35595952, 2022). "Type 2 diabetes mellitus (T2DM) is a metabolic disease characterized by a decrease in pancreatic β-cell mass and function, and represents a failure to compensate for the high insulin demand of homeostatic model assessment of insulin resistant (HOMA-IR) states." (PMID 36704100, 2022). "Inducing the differentiation of non-islet cells into islet-like cells to produce insulin has shown great potential in diabetes treatment." (PMID 36551213, 2022). "The study provides evidence that PEGDA microencapsulated canine islets reversed the signs of diabetes without immunosuppression and led to states of insulin-independence or significantly lowered insulin requirements in the recipients." (PMID 35613086, 2022). "Even in patients not having been diagnosed with diabetes prior to PD, decreased insulin levels and hyperglycemia have been observed due to a reduction in insulin-producing β-cells." (PMID 35625491, 2022). "Diabetes is a chronic disease in which blood sugar levels rise due to inadequate insulin output or when the cells do not respond well to insulin." (PMID 36359308, 2022). "In the current realm of diabetes treatment, there exists a need to discover effective immunotherapy methods, as current treatment by daily insulin injection(s) is not a sustainable way to treat diabetes and is not a cure." (PMID 35336018, 2022). "Diabetes mellitus (DM) is a chronic disease that arises when the pancreas produces insufficient insulin or when the body's insulin is not used correctly." (PMID 36419111, 2022). "Most of the data on the outcomes of COVID-19 patients with pregnancies complicated by diabetes and taking insulin is lacking." (PMID 36079820, 2022). "Neither the type of diabetes nor insulin intake was significantly correlated with the development of hirsutism." (PMID 36654645, 2022). "Hyperglycemia can develop in patients with diabetes when insulin is not produced at all or produced in insufficient quantities, or when its effects are not as potent as they should be." (PMID 36249656, 2022). "And this has been reported to be mainly associated with factors such as older age, longer duration of diabetes, insulin therapy, nonadherence to medications, poor diet adherence, and physical inactivity." (PMID 35249547, 2022). "We found that diabetes significantly increased ratio of p-AKT/AKT while decreased p-GSK3α/GSK3α; and AS-IV administration strikingly reversed effects of high glucose + high insulin on AKT and GSK3." (PMID 35341134, 2022).
diabetes (continued). "The group reporting taking insulin consumed grains more frequently, while consuming snack/sweet and alcohol less frequently compared to participants without diabetes." (PMID 36014790, 2022). "In patients with advanced colorectal cancer patients treated with different FOLFOX regimens those with diabetes were maintained on required doses of insulin during the course of treatment but the extent of insulin adjustment during treatment was not specified." (PMID 34436039, 2021). "In the case of diabetes, once pancreatic islets are damaged by initiating factors, antigen-presenting cells (APCs) activate helper CD4+ T cells, activated in the course of diabetogenesis by peptides present in the β f insulin." (PMID 34836227, 2021). "However, insulin is generally prescribed to T1DM, and to the more severe cases of T2DM, who often have (diabetes related) micro- and macrovascular complications." (PMID 34931295, 2021). "The prescribing of insulin is affected by the organisation of care and where in the health system (e.g. in the hospital or in primary healthcare [PHC]) people can receive their diabetes care." (PMID 33483763, 2021). "This resulted in a delayed use of insulin but the patient eventually started using insulin when their diabetes was not controlled with oral medication alone." (PMID 34616293, 2021). "Our data indicate that preventing NF-κB activation in insulin-expressing cells during the fetal period has a significant long-term effect on diabetes incidence that is not transmitted to the next generation." (PMID 33414444, 2021). "Our findings suggest that the acute effects of OBG on glucose and insulin responses in subjects without diabetes can be extrapolated to people with diabetes." (PMID 33608654, 2021). "It has been recommended that the management of diabetes in GCK-MODY pregnant women should be guided by assessment of fetal growth by serial ultrasounds, and institution of insulin therapy when the abdominal circumference is ≥ 75th percentile, considered as a surrogate for the fetal genotype." (PMID 35069449, 2021). "Independent from the classical PI3K/AKT pathway, insulin signaling may be further transmitted via the RAS/MAPK pathway in cardiac diseases and diabetes." (PMID 34203572, 2021). "This study also showed significant regional variation in CVDs and diabetes medicines dispensing with low CVDs and diabetes medicines dispensing rates and very low to no dispensing of insulin in some governorates that the Syrian government partly controlled." (PMID 34645430, 2021). "Type 2 diabetes mellitus (T2DM) accounts for about 90%, and this disease is due to the lack of insulin responses in the body, which is associated with profound changes of glucose and lipid metabolism." (PMID 34440929, 2021). "Based on the full model, the variables skin thickness, blood pressure, and insulin are not significant predictors of diabetes at 5% significance level." (PMID 34299797, 2021). "In type 2 diabetes mellitus or non-insulin dependent diabetes mellitus (NIDDM) (formerly known as adult diabetes), insulin resistance seems to be the predominant factor and occurs from defects in insulin secretion and a low tissue sensitivity to insulin." (PMID 36699147, 2021). "For adults with diabetes, the body either does not produce enough insulin or its cells are insulin resistant." (PMID 34661545, 2021). "Even in individuals without diabetes, reduced insulin-mediated glucose utilization correlates with increased coronary artery disease." (PMID 34075130, 2021). "According to the 2012 American Diabetes Association (ADA) guidelines, SMBG is recommended at least thrice daily for those on multiple insulin therapy and a minimum once daily for noninsulin users." (PMID 34704954, 2021). "In contrast, the 17D5 no-diabetes rats had mostly normal islets, with insulin+ cells representing 76 ± 3% of islet cells." (PMID 33815287, 2021).
diabetes (continued). "Diabetes Mellitus (DM) is a metabolic disease characterized by chronic hyperglycemia due to absent or inadequate insulin secretion, combining with defective action on target tissues, depending on the type of diabetes." (PMID 34299683, 2021). "Islets immunostained with anti-insulin and anti-glucagon antibodies showed that their number per area of the pancreas (islet density) was similar between the vehicle-treated groups and reduced (P<0.0001) in STZ-induced diabetes." (PMID 33746901, 2021). "Diabetes is described as a “serious, chronic disease that occurs either when the pancreas does not produce enough insulin, or when the body cannot use the insulin it produces effectively”." (PMID 33801378, 2021). "Specifically, we used a large nationwide cohort of postmenopausal women to determine the risk of glaucoma onset in subjects with no diabetes, IFG, new onset diabetes, diabetes treated with oral hypoglycemic medication, or diabetes treated with insulin." (PMID 34521935, 2021). "Therefore, future studies on the effects of CJHE in the PPARγ expression and insulin sensitivity in the differentiated adipocytes will be also critical to determine utility of CJHE for insulin resistance and diabetes." (PMID 33804020, 2021). "Because the patient did not have diabetes mellitus, his insulin secretion and insulin resistance were examined." (PMID 33614349, 2021). "Diabetes mellitus (DM) is a metabolic disease characterized primarily by hyperglycemia, as a result of the absolute absence of insulin, resistance to the action of insulin, or both." (PMID 34295258, 2021). "BpOmpW re-exposure in insulin-resistant mice maintained an activated T-cell status and high IFN-γ recall responses from CD4, CD8, and NKT cells, which would be essential to protect people with diabetes from melioidosis." (PMID 34966388, 2021). "At 1 year, 48.0% (591 of 1231) of new oral diabetes medications and 38.5% (548 of 1423) of new insulin prescriptions filled at discharge were no longer being filled." (PMID 34673963, 2021). "Subjects with diabetes on insulin as compared with those without diabetes exhibited a non-significant increased prevalence of severe hyposmia/anosmia (OR 1.68, 95% CI 0.96–3.00)." (PMID 34884338, 2021). "Before matching, insulin users presented higher proportions of young age, young ages at diabetes diagnosis, medications use, hepatitis infection than insulin nonusers." (PMID 34118892, 2021). "In addition, we conducted a stratified analysis of the relationship between the TyG index and increased arterial stiffness according to the potential modifiers, including sex, age, HbA1c, duration of diabetes, SBP, and insulin therapy." (PMID 33888131, 2021). "Our findings suggest that RV improves glucose and insulin levels in subjects with type 2 diabetes mellitus (T2DM) and aged 45–59 years, regardless of the duration of the intervention." (PMID 33430470, 2021). "Surprisingly, most of the respondents did not view diabetes as a severe disease, probably due to their belief that people who do not take insulin to treat their diabetes have mild disease." (PMID 33579243, 2021). "The transient maternal hyperglycemia in women without diabetes after ACS-betamethasone can be limited by the concurrent use of insulin." (PMID 33588801, 2021). "Diabetes is a chronic disease that occurs when the pancreas does not produce enough insulin or when the body does not use the insulin effectively." (PMID 34200822, 2021). "This type of diabetes belongs to the subgroup defined as early diagnosis, typically before age of 25, and is not insulin dependent." (PMID 34444990, 2021). "Type 2 diabetes tends to occur in adults; when people have this type of diabetes, the body does not use the insulin it produces properly." (PMID 33628230, 2021). "Among patients in the current study with diabetes only and diabetes and CKD, the risk for recurrent CVD events was higher for those taking versus not taking insulin." (PMID 33648518, 2021).
diabetes (continued). "The variable for diabetes was missing in more than 50% of cases, and we were not able to differentiate gestational diabetes mellitus treated with or without insulin from one another, or from preexisting (non-pregnancy-related) diabetes." (PMID 34415907, 2021). "Results from the Diabetes Control and Complications trial (DCCT) were reported in 1993 and illustrated that intensive insulin therapy, using three or more insulin injections or insulin pump therapy, was effective at reducing long-term complications of diabetes." (PMID 37745178, 2021). "Once DHEAS levels decline with age, there is an increasing prevalence of diabetes, which is why DHEA supplementation may be a new therapeutic way to restore impaired insulin signal transduction in skeletal muscle." (PMID 35056103, 2021). "This study also demonstrated a significant increase in peripheral insulin sensitivity in patients with type 2 diabetes mellitus after 30 HBOT sessions, which was not seen in those exposed to normobaric conditions." (PMID 34684171, 2021). "We obtained pancreatic sections from organ donors and immunofluorescence staining with NKX6.1 and insulin was performed to characterize NKX6.1 expression in subjects with or without type 2 diabetes mellitus (T2DM)." (PMID 33711989, 2021). "Lack of insulin or its inadequacy in cases of diabetes leads to alterations in the pathway, which greatly influence the disease prognosis." (PMID 34225729, 2021). "Activating variants in the ABCC8 gene led to an increased probability of opening of the potassium channel, therefore preventing any activation of the voltage-dependent calcium channel and any glucose-induced insulin secretion, leading to NDM, early onset diabetes, and MODY." (PMID 34631896, 2021). "Considering that T2D is by far the most common type of diabetes, in this review, we focus on evidence behind DCM in T2D to discuss the roles of PPARα not only in energy metabolism but also in insulin resistance, oxidative stress, inflammation, and Ca2+ handling regulation." (PMID 33397369, 2021). "For instance, a diabetes-oriented WBAN enables continuous blood glucose monitoring, and when abnormal values are detected, communicates to an external smart healthcare service and/or activates an insulin pump actuator that delivers insulin into the body." (PMID 34696099, 2021). "In the “other types” of diabetes group we find almost the same frequency of insulin and oral medication use and observed 5% without any medications for diabetes." (PMID 34412660, 2021). "Over two decades, the proband required minimal insulin to maintain HbA1c of 5.7%–6.5%, and she did not experience ketosis or other diabetes-related complications." (PMID 34032641, 2021). "Immediate insulin treatment did not result in protection against diabetes-related alterations of TNFα expression in any of the gut segments." (PMID 34572059, 2021). "While it did not account for many of the secondary actions of insulin, Levine’s theory of insulin working on cell membranes was a breakthrough in diabetes research." (PMID 34717956, 2021). "Therefore, understanding the underlying mechanisms of OCN regulation of glucose metabolism and dissecting its interplay with insulin and IGF1 will shed light on how to use it to treat diabetes in an effective and safe manner." (PMID 34489478, 2021). "While oral antihyperglycemic agents are indicated for many patients with type 2 diabetes, some patients require insulin injections, with or without oral antihyperglycemic agents, in the advanced stages of diabetes." (PMID 33502325, 2021). "Tudor in the San Luis Valley Diabetes Study, Colorado found an odds ratio for any DR (95% CI) = 8.45 (2.65-26.97), in patients on insulin vs. no medications." (PMID 34912295, 2021). "Insulin-requiring GDM was defined as no insurance claims for diabetes mellitus and a fasting blood glucose level of < 126 mg/dL before pregnancy, and initiation of insulin treatment during pregnancy." (PMID 34446090, 2021).
diabetes (continued). "Pancreatic insulin content in the DIO mice (45 ng/mg pancreas) was much higher than that in the db/db mice (10 ng/mg), confirming that DIO mice are a model of early-stage diabetes, while db/db mice serve as an advanced-stage model." (PMID 34768897, 2021). "Of these, 98.5%, 80.9%, and 60.3% of hospitals administered a beverage to patients without diabetes, patients with diabetes not taking insulin, and patients with diabetes taking insulin, respectively." (PMID 34044894, 2021). "Insulin is also used for treating diabetes, and the effects of long-term insulin therapy on mitochondrial function have also not been studied enough." (PMID 34205752, 2021). "Typically, adolescents with diabetes require 2 pens/month, with overall costs considerable higher than US$8–10 for soluble insulin, NPH insulin at $9–10, with premixed insulins at $10–15 all at 1,000 IU (i.e., 10 ml of 100 IU/ml) with each 10 ml vial lasting ~25–30 days." (PMID 34249838, 2021). "Diabetes mellitus, as a chronic metabolic disease, is characterized by hyperglycemia due to inadequate insulin production by pancreatic beta cells (T1DM) or insulin resistance (inability to respond properly to insulin)(T2DM)." (PMID 34077450, 2021). "Thus, in order to reduce misclassification, we employed the epidemiologic definition of T1D used by the Swedish national diabetes register (NDR), which is based on age at diagnosis and insulin medication." (PMID 34220961, 2021). "We also note that our dysglycemia outcome predominantly reflects prediabetes and early undiagnosed diabetes; therefore, the current results do not inform on the role of insulin homeostasis traits in diabetes of longer duration." (PMID 34206745, 2021). "Several pathways have been proposed to explain how hyperglycemia and specifically the metabolic state of diabetes generate damage and oxidative stress in cells and tissues requiring (or not) insulin for efficient glucose uptake." (PMID 34069422, 2021). "Materials and Methods: The study group consisted of patients with type 2 diabetes mellitus without insulin treatment." (PMID 34833467, 2021). "Insulin therapy is recommended as the first line in those that present initially in diabetic ketoacidosis or hyperosmolar hyperglycemic nonketotic syndrome." (PMID 33435250, 2021). "Despite the huge improvements in diabetes technologies, such as glucose monitoring systems and insulin pumps, many people with diabetes do not meet glycemic control targets and would benefit from greater flexibility and more individualized diabetes therapy." (PMID 33587045, 2021). "It is especially the case in patients with poorly controlled diabetes and hyperglycemia and affects primarily cells in which the glucose uptake is not controlled by insulin." (PMID 33673618, 2021). "Insulin and HOMA-IR levels are increased in the initial phase of type 2 diabetes mellitus, and, in patients with long-term diabetes, these indicators could be normal." (PMID 33921361, 2021). "From these data, it could be assumed that diabetes, and also insulin use itself, do not correlate with the severity of tibial atherosclerosis and that other factors, for example, wounds and infections, rather than extensive atherosclerosis seem to expose diabetics to higher limb loss." (PMID 33225841, 2021). "Among the most well-known types of diabetes is type 1 diabetes, where the body does not produce insulin or in insufficient quantities, which develops due to lifestyle changes, viral infections, toxins ingestion, and genetic predisposition." (PMID 33802826, 2021). "Irs2−/− mice are also insulin-resistant, but unlike Irs1−/− counterparts, the mice develop diabetes and have a much shorter lifespan." (PMID 34680948, 2021). "Given the important role that the insulin-producing pancreatic islet and β-cells play in the development of the metabolic syndrome and diabetes, we also sought to ensure that the insulin infusion did not downregulate fetal pancreatic β-cell mass." (PMID 34917036, 2021).